USP39 (ubiquitin specific peptidase 39)
Diseases named in the same sentence as USP39 in open-access papers (continued):
Sharing a sentence is not in itself a finding about the gene and the disease.
lung adenocarcinoma (3 papers, 2020 to 2024). A carcinoma that arises from the lung and is characterized by the presence of malignant glandular epithelial cells. "Knockout of USP39 can inhibit tumor genesis, induce cell apoptosis, and inhibit lung adenocarcinoma cell metastasis." (PMID 36046375, 2022). "Here, by applying a gene set enrichment analysis (GSEA) on lung adenocarcinoma tissues and metabolite set enrichment analysis (MSEA) on NSCLC cells depleted of USP39, we identified a previously unknown link between USP39 and the metabolism in NSCLC cells." (PMID 39695108, 2024).
nasopharyngeal carcinoma (3 papers, 2020 to 2025). A carcinoma arising from the nasopharyngeal epithelium. "It is reported that LINC00520 exhibits pro-oncogenic function in nasopharyngeal carcinoma by regulating the miR-26b-3p/USP39 axis." (PMID 32466797, 2020). "LINC00520 affects the process of malignant progression of nasopharyngeal carcinoma by antagonizing the expression level of USP39 regulated by miR-26b-3p, suggesting that USP39 may play a role as a regulator in nasopharyngeal carcinoma." (PMID 40672756, 2025).
acute myocardial infarction (2 papers, 2023 to 2025). Necrosis of the myocardium, as a result of interruption of the blood supply to the area. "The loci we associated with coronary artery disease (FOXC1), myocardial infarction (USP39), and atrial fibrillation (SLC35F1 and SSPN) through their effects on RHR have been associated with these cardiovascular diseases in recent studies." (PMID 37532724, 2023).
cervical squamous cell carcinoma (2 papers, 2023 to 2025). A squamous cell carcinoma arising from the cervical epithelium. "Overall, the results suggest that USP39 facilitates cell proliferation and decreases cell apoptosis rate in cervical squamous cell carcinoma." (PMID 37957720, 2023). "Additionally, USP39 silencing was demonstrated to suppress cell proliferation potential and promote cell apoptosis in cervical squamous cell carcinoma in vitro." (PMID 37957720, 2023). "Finally, we wanted to explore whether SIRT7 regulates oxidative stress in cervical squamous cell carcinoma via USP39 and FOXM1." (PMID 37957720, 2023). "According to the GEPIA analysis, the expression of USP39 and FOXM1 was in positive correlation in the cervical squamous cell carcinoma (R = 0.36, p-value = 1e-10)." (PMID 37957720, 2023). "This positive feedback was then further verified using rescue assays, which indicated that indeed SIRT7 promoted the autophagy and inhibited ROS production through USP39 and FOXM1 in cervical squamous cell carcinoma." (PMID 37957720, 2023). "SIRT7/USP39/FOXM1 is highly expressed in CSCC, but whether the pathogenesis in cervical squamous cell carcinoma patients is inhibited by acetylation of USP39 at the k428 site still needs further study." (PMID 37957720, 2023). "Moreover, SIRT7 expression was revealed to be downregulated after USP39 silencing, which was reversed after FOXM1 overexpression in cervical squamous cell carcinoma cells." (PMID 37957720, 2023).
esophageal cancer (2 papers, 2022 to 2024). A primary or metastatic malignant neoplasm involving the esophagus. "The strong correlation between high expressions of USP39 with poor prognosis prompted us to investigate the roles of USP39 in the chemoresistance of esophageal cancer cells." (PMID 35627203, 2022). "The transwell assay showed that the overexpression of USP39 promoted the migrative and invasive capabilities of esophageal cancer cells, while the suppression of USP39 exerted the opposite effect." (PMID 35627203, 2022). "Consistent with the results in vitro, overexpression of USP39 significantly promoted tumor growth, whereas the depletion of USP39 inhibited tumor growth compared with the corresponding control group, suggesting that USP39 promotes esophageal cancer cell growth." (PMID 35627203, 2022). "Finally, we focused on the function of USP39 in esophageal cancer." (PMID 35627203, 2022).
head and neck squamous cell carcinoma (2 papers, 2025). A squamous cell carcinoma that arises from any of the following anatomic sites: lip and oral cavity, nasal cavity, paranasal sinuses, pharynx, larynx, and salivary glands. "LC-MS/MS analysis showed that USP39 was expressed at higher levels in head and neck squamous cell carcinoma (HNSCC) tissues than in adjacent normal tissues." (PMID 40672756, 2025).
oral squamous cell carcinoma (2 papers, 2019 to 2020). "Knockdown of USP39 by lentivirus-mediated RNA interference suppresses the growth of oral squamous cell carcinoma." (PMID 30898977, 2019).
serous ovarian carcinoma (2 papers, 2021 to 2022). "We here show that USP39, a component of the spliceosome, is frequently overexpressed in high-grade serous ovarian carcinoma (HGSOC) and that an elevated level of USP39 is associated with a poor prognosis." (PMID 33731694, 2021).
viral infection (2 papers, 2024 to 2025). "Then, we delineate the function of USP39 in maintaining epithelial morphology, resistance to viral infection, vascular remodeling, and pathological states." (PMID 40990019, 2025). "In contrast to USP39, which showed a slightly up‐regulated expression level after viral infection, we did not see changes in the total protein level of USP33 after viral infection in a variety of cell lines." (PMID 39301916, 2024).
astrocytoma (1 paper, 2022). "The H‐score of USP39 expression levels was higher in astrocytoma, GBM, oligodendroglioma and metastatic glioma than in normal brain tissues." (PMID 33811456, 2022).
B-cell lymphoma (1 paper, 2024). "Because the spliceosome component of USP39 has a role in B-cell development and in controlling the rearrangement of immunoglobulin genes, targeting USP39 could represent a promising therapeutic strategy for treating B-cell lymphoma." (PMID 39664521, 2024).
bladder cancer (1 paper, 2022). "Next, to determine the expression of USP39 protein in two additional cell lines (RT4, a human urinary bladder papilloma cell line, and MBT2 cells, a mouse cell line derived from a bladder cancer), we performed immunohistochemistry with anti-USP39 antibody." (PMID 35440748, 2022).
brain tumor (1 paper, 2022). "Finally, the expression levels of USP39/ADAM9 in the brain tumor were detected by western blotting and IHC analysis." (PMID 33811456, 2022). "In addition, we detected the expression levels of USP39, ADAM9 and integrin β1 in the brain tumor." (PMID 33811456, 2022).
cervical cancer (1 paper, 2023). A primary or metastatic malignant neoplasm involving the cervix. "We hypothesized that SIRT7 may regulate the autophagy and oxidative stress in cervical cancer through USP39." (PMID 37957720, 2023). "Therefore, we assessed if USP39 acetylation was affected by SIRT7 in cervical cancer cells." (PMID 37957720, 2023). "However, the relationship between SIRT7 and USP39 in cervical cancer is not known." (PMID 37957720, 2023).
endotoxemia (1 paper, 2025). "Using bone marrow-derived macrophages and an endotoxemia mouse model, we found that NAT10 is significantly upregulated in response to lipopolysaccharide (LPS) due to the deubiquitinating enzyme USP39, which stabilizes the NAT10 protein." (PMID 40593466, 2025).
gastric tumor (1 paper, 2024). "Immunoblotting of USP39 in the lysates of tumor and paratumor tissues revealed that USP39 protein was indeed highly elevated in gastric tumor tissues, which is consistent with the USP39 mRNA expression in tumor tissues obtained from The Cancer Genome Atlas database." (PMID 39260689, 2024).
Hepatic steatosis (1 paper, 2023). Steatosis is a term used to denote lipid accumulation within hepatocytes. "Taken together, these results suggest that Usp39-HKO mice are more susceptible to fatty liver disease." (PMID 37923718, 2023). "Usp39 deficiency results in an isoform of Hsf1 that undergoes degradation by nonsense-mediated mRNA decay, which in turn leads to impaired autophagy and to hepatic steatosis." (PMID 37923718, 2023). "Importantly, our results suggest that loss of Usp39 induces hepatic steatosis partially by impairing Hsf1-regulated autophagy." (PMID 37923718, 2023). "Consistent with HFD model, hepatic-specific Usp39 deletion exacerbated hepatic steatosis induced by the MCD diets." (PMID 37923718, 2023). "Our results show that hepatocyte-specific Usp39 deletion in mice leads to spontaneous hepatic steatosis." (PMID 37923718, 2023). "Collectively, these results suggest that hepatic steatosis due to Usp39 depletion is partially mediated by Hsf1 downregulation and the subsequent impairment in autophagy." (PMID 37923718, 2023). "Usp39-HKO mice exhibited more pronounced hepatic steatosis and fibrotic formation with HFD feeding." (PMID 37923718, 2023).
liver fibrosis (1 paper, 2023). "Depletion of Usp39 induced liver fibrosis as assessed by Sirius red staining and qPCR analysis of fibrosis markers." (PMID 37923718, 2023). "A combined lipidome and transcriptome analysis showed that liver fibrosis and steatosis were highly enriched in Usp39-HKO mice." (PMID 37923718, 2023).
monoclonal gammopathy of undetermined significance (1 paper, 2024). "Remarkably, Gene Set Enrichment (GSE) unveiled a significant upregulation of USP39 mRNA levels from monoclonal gammopathy of undetermined significance (MGUS) to the MM stage, compared to healthy individuals." (PMID 39736693, 2024).
multiple myeloma (1 paper, 2024). "Further investigations are required to determine the role of USP39 in the mechanisms of BTZ resistance in multiple myeloma." (PMID 39736693, 2024). "Using an siRNA approach, we clearly demonstrated that the depletion of USP39 is capable of overcoming BTZ resistance in multiple myeloma cells." (PMID 39736693, 2024). "To investigate the effects of targeting USP39 on the response of multiple myeloma (MM) cells to bortezomib (BTZ), we performed experiments utilizing both BTZ-sensitive (U266) and BTZ-resistant (U266R) MM cell lines, with the latter previously developed in our laboratory." (PMID 39736693, 2024).
myeloma (1 paper, 2024). "Collectively, our gain-of-function and loss-of-function experiments strongly suggest that targeting USP39 modulates the migratory capacity of myeloma cells through the regulation of ZEB1 expression." (PMID 39736693, 2024). "To determine whether overexpression of USP39 could impact the sensitivity of myeloma cells to BTZ, we used U266 and KMM1 cells stably transfected with lentiviral particles encoding Myc or Myc-USP39." (PMID 39736693, 2024). "Therefore, we sought to determine whether ZEB1 depletion could mimic the effect of USP39 inhibition on myeloma cell fate." (PMID 39736693, 2024).
neuroblastoma (1 paper, 2025). Neuroblastoma (NB) is the most common solid, extracranial childhood tumor. "Additionally, single-cell RNA sequencing demonstrated that USP39 plays a role in regulating RNA splicing in neuroblastoma." (PMID 40672756, 2025).
non-alcoholic fatty liver disease (1 paper, 2023). "We demonstrate that Usp39 expression is downregulated in hepatic tissues of non-alcoholic fatty liver disease (NAFLD) and non-alcoholic steatohepatitis (NASH) subjects." (PMID 37923718, 2023).
rectal cancer (1 paper, 2024). A primary or metastatic malignant neoplasm that affects the rectum. "Among the candidate USPs, USP39 and USP36 expression differed significantly, consistent with observations in patients with colon and rectal cancer." (PMID 38876304, 2024).
sarcoma (1 paper, 2017). A usually aggressive malignant neoplasm of the soft tissue or bone. "Collectively, most of sarcoma tissues in Oncomine database had a higher expression of USP39 compared to that in normal issues." (PMID 28403900, 2017). "The USP39 mRNA expression of all the sarcoma tissues in Barretina sarcoma and Detwiller sarcoma had a significant increase compared to that in normal issues (p < 0.05)." (PMID 28403900, 2017). "Besides, DNA copies of USP39 in sarcoma tissues also have the same tendency as that of mRNA expression." (PMID 28403900, 2017).
Sepsis (1 paper, 2024). Sepsis is defined as life-threatening organ dysfunction caused by a dysregulated host response to infection. "Furthermore, USP39 is downregulated in LPS-induced sepsis and it can decrease the release of proinflammation factors and subsequently sepsis-related inflammation." (PMID 38322269, 2024).
spina bifida (1 paper, 2022). A congenital neural tube defect in which vertebrae are not fully formed. "However, Grhl3NLS/NLS; Usp39+/− embryos appeared to display a much more severe spina bifida phenotype than Grhl3NLS/NLS embryos." (PMID 35440748, 2022).
steatosis (1 paper, 2023). Increased lipid within the cytoplasm of cells. "Our study also showed that Usp39 deficiency in hepatocytes causes autophagy defects and lipid accumulation and thus results in spontaneous steatosis in mice." (PMID 37923718, 2023). "Usp39 deficiency in hepatocytes causes autophagy defects and lipid accumulation and thus leads to spontaneous steatosis." (PMID 37923718, 2023). "Here the authors report that spliceosome component Usp39 deletion in mice leads to spontaneous steatosis and impaired autophagy through the regulation of alternative splicing." (PMID 37923718, 2023). "Hepatocyte-specific Usp39 deletion in mice leads to increased lipid accumulation, spontaneous steatosis and impaired autophagy." (PMID 37923718, 2023).
cancer (45 papers, 2008 to 2026). A tumor composed of atypical neoplastic, often pleomorphic cells that invade other tissues. "To identify mediators of USP39 growth-promoting properties, we used luciferase reporter constructs under transcriptional control of various promoters specific to seven canonical cancer-associated pathways." (PMID 31332287, 2019). "A recent study highlighted the potential role of Ubiquitin Specific Peptidase 39 (USP39) as a valuable immune-related biomarker with both diagnostic and prognostic utility across multiple cancer types, especially PDAC, emphasizing its promise as a therapeutic target for cancer immunotherapy." (PMID 40565031, 2025). "In addition, an exome sequencing study in BC patients demonstrated that USP39 regulates cancer-associated tumor suppressors, including CHEK2, and has a tumor-inducing effect." (PMID 40990019, 2025). "USP39 regulates cancer-associated tumor suppressors including CHEK2 and induces tumorigenesis." (PMID 40990019, 2025). "Moreover, aberrant USP39 expression is linked to tumorigenesis in various cancers including breast, colorectal, lung, and brain cancers." (PMID 39736693, 2024). "Additionally, we show that USP39 deficiency severely impairs cancer cell growth both in vitro and in vivo." (PMID 39695108, 2024). "For example, never-smokers displayed a greater proportion of hypomethylated differentially methylated regions (hypoDMRs) and a greater number of recurrently hypomethylated promoters, including those of ASPSCR1, TOP2A, DPP9, and USP39, all previously linked to cancer." (PMID 37742993, 2023). "This review provides a comprehensive overview of USP39’s structure, physiological function, and promise as a biomarker in cancer diagnosis and treatment." (PMID 40990019, 2025). "Most of the relevant studies on USP39 in malignant tumors have been limited to phenotypic and functional studies, lacking further exploration of mechanisms and pathways." (PMID 40672756, 2025). "Based on the current understanding of USP39’s regulatory mechanisms, further refinement of cancer treatment strategies can be achieved." (PMID 40672756, 2025). "These novel cancer treatment strategies based on the unique characteristics of USP39 are of great significance for the development of precision medicine." (PMID 40672756, 2025). "A detailed overview of the specific mechanisms of action of USP39 in various cancers is provided below." (PMID 40990019, 2025). "In summary, USP39 holds great potential as a clinical biomarker and therapeutic target in oncology, providing novel approaches and pathways for precise cancer detection and effective treatment." (PMID 40672756, 2025). "Future research is required to comprehensively explore the specific mechanisms through which USP39 governs malignant progression across various types of cancers." (PMID 40672756, 2025). "USP39 in ESCC not only drives the growth of cancer cells but also correlates with chemotherapy resistance." (PMID 40990019, 2025). "Growing evidence highlights USP39’s critical involvement in the progression of malignant tumors, where it acts as a pro-tumor factor, influencing cancer growth, proliferation, and metastasis." (PMID 40672756, 2025). "In a word, the research efforts dedicated to USP39 have allowed the discovery of a wide range of USP39’s regulatory roles in the development of malignant tumors." (PMID 40672756, 2025). "According to recent research, USP39 is significantly expressed in a broad spectrum of cancerous tumors." (PMID 39781342, 2025). "USP39 shows modulation of multiple biological functions of malignant tumors in HCC, giving it potential as a pro-tumorigenic factor." (PMID 40672756, 2025).